TRPV2 (transient receptor potential cation channel subfamily V member 2)
Diseases named in the same sentence as TRPV2 in open-access papers (continued):
Sharing a sentence is not in itself a finding about the gene and the disease.
cancer (continued). "Xenograft tumor-based in vivo approaches in cancer prostate cells suggest that TRPV2 silencing diminishes the weight of tumors and the expression of invasion markers, namely MMP2, MMP9 and cathepsine B." (PMID 31275168, 2019). "The use of TRPV2 as an antitumor target is certainly an exciting prospect in drug research but should be considered with caution for cancers other than PCa." (PMID 31288452, 2019). "Here, we utilized the usually ineffective charged fraction of doxorubicin and shuttled it into cancer cells via cation permeable TRPV2 channels, allowing us to achieve the desired effect using substantially lower doses of doxorubicin." (PMID 31680972, 2019). "A review of the literature revealed that aberrant expression of CKMT1A, GCNT1, NCALD, NFKBIB, NOMO3/Nodal, SLC16A5, or TRPV2 was correlated with cancer." (PMID 31363162, 2019). "We previously reported the overexpression of TRPV2 in cancer stem cells derived from ESCC cell lines, and the present results from the pathway analysis were consistent with these findings." (PMID 31690728, 2019). "In the field of oncology, many researchers reported that TRPV2 similarly regulated cell death in cancer cells or cancer migration/invasion." (PMID 31690728, 2019). "The transient receptor potential vanilloid type two (TRPV2) channel emerged as a candidate channel in several deadly cancers promoting proliferation and resistance of cancer cells to apoptotic-induced cell death." (PMID 30733502, 2019). "Previous studies reported that TRPV2 was involved in cancer progression, migration, and invasion as well as in the therapeutic effects of anticancer drugs." (PMID 31690728, 2019). "In fact, in a xenograft mouse model, the injection of TRPV2-overexpressing GSCs lead to the formation of smaller tumor mass, characterized by cancer cells, with a reduced mitotic index and a more mature glial phenotype with respect to the control counterpart." (PMID 30845786, 2019). "Further investigation of the activity of TRPV2 in cancer is needed to determine the feasibility of utilizing cannabinoids to target this cation channel as a therapeutic strategy." (PMID 29066974, 2017). "We report that LL-37 induces migration of three cancer cell lines by activating the TRPV2 calcium-permeable channel and recruiting it to pseudopodia through activation of the PI3K/AKT pathway." (PMID 26993604, 2016). "The implication of TRPC5 in the progression and chemoresistance of various cancers suggests, as in the case of TRPV2, that studying the effects of astringents on these channels may have important implications for oral oncology." (PMID 41586439, 2026). "Finally, PL derivatives inhibited cancer cell migration in vitro and suppressed metastasis in vivo, underscoring the therapeutic potential of selective TRPV2 antagonists." (PMID 41879799, 2026). "With BG's excellent biosafety profile and US's clinical approval, this dual‐gating strategy offers a safe and efficient method for the precise treatment of cancers with high TRPV2 expression, providing new insights into the design of calcium‐overload‐based cancer therapies." (PMID 40013983, 2025). "Moreover, other genes upregulated in distinct but also specific stimuli like PPA1, GADD45B, C1D, TRPV2 and RPS14 were associated with DDR, cancer and apoptosis." (PMID 39623312, 2024). "Given the high expression of TRPV2 in cancer cells, our subsequent investigation aimed to determine whether the activation of TRPV2 contributes to cancer progression using cannabidiol, a TRPV2 activator." (PMID 39334351, 2024). "The TRPV2 study involved a total of 1524 cancer samples both at the mRNA and protein level." (PMID 37240443, 2023). "Additionally, the overexpression of TRPV2 attenuated the stemness of cancer stem-like cells by reducing marker levels." (PMID 37733242, 2023). "The TRPV2 immunoreactivity score correlated with the stage of the cancer." (PMID 37240443, 2023).
cancer (continued). "However, the endogenous modulation and pathophysiological function of TRPV2 in cancer remains largely unexplored." (PMID 36081847, 2022). "Therefore, TRPV2 is a promising target for drug discovery and development of novel therapeutics in cancer." (PMID 36081847, 2022). "TRPC4, TRPV2, TRPV1, and TRPV3 loss variations were found in nearly all cancers." (PMID 35831825, 2022). "In cancer stem cells, TRPV2 inhibits GSC proliferation both in vitro and in vivo." (PMID 35887116, 2022). "f-TRPV2 and s-TRPV2 have opposite trends of expression in cancer cells compared to normal cells." (PMID 36045706, 2021). "Importantly, such cancer therapeutic efficacy was also observed in A549 xenografts with in situ transfection of TRPV2, indicating this technique is able to work across multiple tumour types without the limitation of endogenous TRPV2 expression." (PMID 32807785, 2020). "In our hands, application of TRPV2 agonist cannabidiol (CBD, 50 μM) caused increase of basal tension and enhancement of the spontaneous contraction amplitude with both effects being insignificantly smaller in cancer vs. control DSM." (PMID 33184390, 2020). "Such synergistic effect indicates laser-induced TRPV2-PCNH may improve cancer drug resistance by inhibiting cancer stemness." (PMID 32807785, 2020). "Therefore, blockade of β-catenin by TRPV2–PCNH mediated phototherapy offers an attractive mechanism-based therapeutic strategy for cancer treatment." (PMID 32807785, 2020). "TRPV2-mediated signaling pathways modulate some pathological processes in cancer." (PMID 32751388, 2020). "In the current study, we develop a photothermogenetics approach using NIR light-activatable CNH complexes, in which tissue-penetrating NIR light is locally converted to thermal energy at levels that are sufficient to stimulate TRPV2 overexpressing cancer cells." (PMID 32807785, 2020). "Notably, tranilast was found to target the TRPV2-overexpressing dehydrogenase 1-positive cancer stem cells (CSCs) isolated from the TE8 ESCC cell line." (PMID 33376561, 2020). "LL-37 was found to stimulate both cell proliferation and migration in multiple forms of cancer and perhaps may involve TRPV2 activation." (PMID 33376561, 2020). "Contractile action of CBD suggests that TRPV2 may be also an important determinant of DSM contractility, although its role in the symptomatic of bladder dysfunction associated with cancer is likely to be small if any." (PMID 33184390, 2020). "Similarly, Gambade and colleagues showed that the translocation of TRPV2 to pseudopodia induced calcium entry and increased cancer cell migration." (PMID 32668787, 2020). "Clinical studies are needed to identify cancer populations that may benefit from TRPV2 as a molecular biomarker and perhaps will open new prospectives to explore TRPV2 as a novel therapeutic target in cancer and metastasis." (PMID 33376561, 2020). "Hence, TRPV2 expression seems to positively or negatively regulate cancer cell growth and proliferation depending on cellular context." (PMID 30733502, 2019). "Recent reports suggest that TRPV2 is involved in the maintenance of cancer stem cells (CSCs)." (PMID 31801263, 2019). "Hence, we investigated the role of TPRV2 in ESCC using a cancer function assay with the knockdown of TRPV2 by siRNA, microarray, pathway, and gene ontology analyses." (PMID 31690728, 2019). "Moreover, the gene ontology analysis revealed that cancer functions, such as cell invasion, angiogenesis, cell migration, cell proliferation, and apoptosis, were down-regulated in TRPV2-depleted ESCC cells." (PMID 31690728, 2019). "k The Cancer Cell Line Encyclopedia (CCLE) database showing TRPV2 expression in cancer cell lines." (PMID 30326911, 2018). "TRPV2 promotes cell migration and the invasive cancer cell phenotype." (PMID 29772843, 2018). "The possibility to use TRPV2 in cancer therapy is still in infancy." (PMID 24709905, 2014).
cancer (continued). "Thus, the loss of homeostatic controls of survival and growth factor-dependent proliferation exerted by TRPV2 channels result in a proliferative advantage for cancer cells." (PMID 24709905, 2014). "Future research should explore the effects of varying US frequencies and intensities on TRPV2 activation, as well as refine BG composition and structure to optimize ion release for more precise therapeutic outcomes, broadening its potential in cancer treatment." (PMID 40013983, 2025). "However, this dual behavior of TRPV2 is not uncommon among cancer-associated genes, an example is TGFβ that can act as a tumor suppressor or tumor promoter according to the tumor stage." (PMID 34671260, 2021). "TRPV2 may affect cancer biology through the regulation of Ca2+ signaling." (PMID 34671260, 2021). "Since we demonstrated that TRPV2 is associated with the mesenchymal cell phenotype, the potential contribution of mesenchymal tumor components should not be disregarded when evaluating the role of TRPV2 in cancer." (PMID 34936030, 2021). "Indeed, AKT phosphorylated form was significantly increased in TRPV2+ cells (p < 0.001) supporting the hypothesis that TRPV2 expression increases cancer aggressiveness." (PMID 32751388, 2020). "This review focuses on the pathophysiological significance of the TRPV2 channel in many kinds of cancers, and we hope to offer the reader a flavor of how the measurable molecular changes in TRPV2 could validate its quality as a cancer biomarker and potential therapeutic target." (PMID 33376561, 2020). "Additionally, since Protein kinase B (PKB), also known as Akt, pathway is involved in supporting several pro-tumoral processes, to assess the potential role of TRPV2 in regulating cancer cell migration, modulation of AKT/PKB pathway was evaluated through Western blot analysis." (PMID 32751388, 2020). "Indeed, previous evidences show that inactivation of TRPV2-mediated signals in cancer leads to an uncontrolled proliferation and cell death-resistance, and that TRPV2 activation increases migratory capability and invasiveness of cancer cells." (PMID 32751388, 2020). "They showed that the regulation of Ca2+ signaling by TRPV2 may affect these cancer functions." (PMID 31690728, 2019). "Since P-gp transporter expression was correlated with drug resistance in cancer cells, CBD-mediated inhibition of P-gp ATPase could underlie this effect of CBD and doxorubicin on inhibition of cell colonies in addition to TRPV2-mediated entry of doxorubicin." (PMID 31680972, 2019). "Therefore, it is plausible that TRPV2 regulates cancer biology via calcium signaling in ESCC." (PMID 31690728, 2019). "We evaluated the distribution of the TRP family in C1–C6 pan-cancer immune subtypes and observed that TRPC4, TRPC6, TRPM4, TRPV2, TRPV4, MCOLN1, and PKD2L1 had the potential to predict the immune subtype." (PMID 36830651, 2023). "In the following section, we provide an overview of how Piezo1/2, TRPC1, TRPC5, TRPM2, TRPM4, TRPM7, TRPV2 and TRPV4 affect cancer cell behavior." (PMID 36158191, 2022). "TRPV1 in KIRC, TRPV2 in LUSC, TRPV3 in BRCA, TRPV6 in LUAD and BRCA, while TRPV4 in KIRC and BRCA differed significantly across different cancer subtypes (P <0.05)." (PMID 35174089, 2022). "It would be also interesting to synthesize and develop pharmacological compounds that target TRPV1, TRPV2, and TRPA1 that were shown to be downregulated in some types of cancers and whose activity enhances differentiation and impairs stemness." (PMID 36142596, 2022). "In particular, we discuss the roles of Piezo1/2, TRPC1, TRPC5, TRPM2, TRPM4, TRPM7, TRPV2, and TRPV4 in mechanosensing and cancer metastasis." (PMID 36158191, 2022). "TRPV2 expression in some tumor cells is significantly higher than that in normal cells, and according to the Cancer Cell Line Encyclopedia (CCLE) database, the expression of TRPV2 is higher in MM cell lines compared to other tumor cell lines." (PMID 34579758, 2021).
cancer (continued). "Like TRPV2, TRPV4 has also been connected to cancers through Rho GTPases that act as major mediators of mechanical signaling." (PMID 34356643, 2021). "Several studies support, both in vitro and in vivo, the anti-cancer effects of cannabidiol (CBD), a transient receptor potential vanilloid 2 (TRPV2) ligand." (PMID 32751388, 2020). "Herein, we present a photothermogenetic approach using light-driven TRPV2-PCNH, and show promising induction of apoptosis in cancer cells and repression of CSC characteristics." (PMID 32807785, 2020). "We demonstrated that TRPV2 was overexpressed in cancer stem cells derived from ESCC, and suggested the potential of tranilast, a TRPV2-specific inhibitor, as a therapeutic agent for cancer stem cells." (PMID 31690728, 2019). "In particular, three out of the selected ‘prostate-associated’ channels are overexpressed in PCa ECs and have marked effects on the main EC properties including proliferation (TRPV2), TEC-mediated crosstalk with cancer cells (TRPC3) and angiogenesis (TRPA1)." (PMID 31288452, 2019). "It is able to reduce in a TRPV2-dependent manner cell proliferation and survival, promoting cell death and enhancement of chemosensitivity in human GBM and other cancer types." (PMID 30845786, 2019). "An interesting report showed that TRPV2 is involved in the maintenance of cancer stem cells (CSCs) from ESCC and that tranilast, a TRPV2-specific inhibitor, decreased the population of CSCs, and is a possible candidate drug for combination therapy of ESCC." (PMID 31083561, 2019). "We therefore examined the mRNA expression of seven cannabimimetic receptors – CNR1 (CB1), CNR2 (CB2), GPR55, TRPV1, TRPV2, TRPA1, TRPM8 – and found them to be differentially expressed amongst the 12 tested cancer cell lines." (PMID 31289609, 2019). "The phototherapeutic efficacy of TRPV2–PCNH may improve drug resistance and inhibit cancer stemness." (PMID 40548119, 2025). "The TRPV1, TRPV2, and TRPV4 receptors play a significant role in cancer pathology." (PMID 40006844, 2025). "The mechanism of these endocannabinoid-targeting drugs varies based on the type of cancer and the receptor, CBR-1, CBR-2, transient receptor potential vanilloid TRPV1 or TRPV2, and whether it is dependent or independent." (PMID 39707578, 2024). "In spite of a critical role established for Ca2+ signaling in both adhesion and actin cytoskeleton dynamics, no study in cancer cells inferred a direct function for the mechanosensitive channel TRPV2 in these processes." (PMID 36744297, 2023). "Moreover, MMP2 and MMP9, which were reported to be downstream of SKA1 or TRPV2 in many other cancers, were found to be downregulated in ESCC cells when SKA1 or TRPV2 was knocked down by siRNAs." (PMID 35813298, 2022). "Recently, it has raised much attention that TRPV2 acts as a cancer biomarker and potential therapeutic target for many cancer types 18, but the specific function in ESCC is not very clear." (PMID 35813298, 2022). "Additionally, TRPC1, TRPC5, TRPM2, TRPM4, TRPM7, TRPV2 and TRPV4 can independently induce EMT in cancer cells." (PMID 36158191, 2022). "Hypermethylation and survival analysis for TRPV6 in LGG and TRPV2 in DLBC, suggested that the hypermethylation status may be drivers in those cancers." (PMID 35174089, 2022). "Additionally, in bladder tumor models, high TRPV2 activity correlates with MMP-2 levels, playing an important role in the progression and invasion of this cancer type." (PMID 34356643, 2021). "Photothermal treatments led to stronger extent of apoptosis in TRPV2-tranfected, as compared to non-transfected, cancer cells." (PMID 32807785, 2020). "Additionally, in LBCs32, TRPV2 Ca2+-activity has been shown to be inhibited by SKF, which displays broad anti-cancer properties." (PMID 30733502, 2019). "Our data suggest that doxorubicin, in doses that do not affect cell viability, when co-applied with TRPV2 activators, significantly reduces viability and proliferation of cancer cells." (PMID 31680972, 2019).
cancer (continued). "The identified TRPV2-interactome-based signature represents a new set of potential biomarkers not only for the study of GBM, but for prognosis and therapeutics of one of the most malignant neoplasms." (PMID 29719613, 2018). "A growing body of evidence implicates members of the TRP family, including TRPV1, TRPV2, and TRPM8, in calcium-mediated signal transduction that regulates proliferation, migration, and metastasis of cancer cells (reviewed by Déliot and Constantin, 2015; Yee, 2015)." (PMID 29066974, 2017). "In addition to SOCE channels, several TRP channels contribute to the migration of cancer cells, including TRP channels TRPC1, TRPM7, TRPM8, TRPV1, TRPV2, and TRPV6." (PMID 26496025, 2015). "In mouse, TRPV2 is activated by IGF-1, a cytokine endowed with potent mitogenic and anti-apoptotic effects on cancer cells; moreover, increased proliferation and survival of human bladder smooth muscle cells, induced by mechanical stress, is associated with increased IGF-1 levels." (PMID 24709905, 2014). "Based on previous studies, we inferred that TRPV2 activity may be mediated by the direct regulation of key proteins, such as MMP2, which are used by cancer cells for invasion." (PMID 24223658, 2013). "TRPV2 is a member of the vanilloid subfamily of transient receptor potential (TRP) channels, originally described for their role in sensory processes, but it is also responsible for cancer growth, metastasis, and chemoresistance through the dysregulation of calcium signaling." (PMID 34671260, 2021). "Therefore, the anti-cancer effects of SKF- and TL on LBCs may be attributed in part to their ability to regulate TRPV2 gene expression by a mechanism that has yet to be elucidated." (PMID 30733502, 2019).